ARRDC4 (arrestin domain containing 4)
Description:
Functions as an adapter recruiting ubiquitin-protein ligases to their specific substrates (By similarity). Plays a role in endocytosis of activated G protein-coupled receptors (GPCRs) (Probable). Through an ubiquitination-dependent mechanism also plays a role in the incorporation of SLC11A2 into extracellular vesicles (By similarity). May play a role in glucose uptake. Participates in innate immune response by promoting IFIH1/MDA5 activation through interaction with TRIM65.
Synonyms: FLJ36045
Tractability: Antibody: UniProt places it where antibodies can reach, with high confidence; its Gene Ontology location is reachable by antibodies, with high confidence; the Human Protein Atlas places it where antibodies can reach. PROTAC: ubiquitination databases record sites on it.
Gene: Protein-coding gene on chromosome 15 (97,960,703 to 97,973,838, forward strand). Ensembl gene ENSG00000140450.
Subcellular location: Early endosome; Cell membrane; Cytoplasmic vesicle
Subcellular location (Human Protein Atlas): Plasma membrane; Vesicles
Gene Ontology:
Molecular function: protein binding; ubiquitin-like ligase-substrate adaptor activity
Biological process: positive regulation of interferon-beta production; positive regulation of ubiquitin-protein transferase activity; protein K63-linked ubiquitination; extracellular vesicle biogenesis; protein transport; protein ubiquitination
Cellular component: cytoplasmic vesicle; early endosome; endosome; plasma membrane; cytoplasm; extracellular vesicle
Genetic constraint (gnomAD): Loss-of-function variants: 35 observed, 35.46 expected, observed/expected ratio (o/e) 0.99, 90% interval 0.75 to 1.31. The upper end of that interval is the gene's LOEUF score, 1.31, which puts it in group 5 of 6, group 1 being the genes least tolerant of losing a copy. Missense variants: 521 observed, 466.31 expected, observed/expected ratio (o/e) 1.12, 90% interval 1.04 to 1.2. Synonymous variants: 205 observed, 178.36 expected, observed/expected ratio (o/e) 1.15, 90% interval 1.02 to 1.29.
Homologues: Orthologues: chimpanzee ARRDC4 (99% identical), dog ARRDC4 (92% identical), guinea pig ARRDC4 (89% identical), pig ARRDC4 (87% identical), rat Arrdc4 (87% identical), mouse Arrdc4 (86% identical), rabbit ARRDC4 (79% identical), macaque ARRDC4 (76% identical), tropical clawed frog arrdc4 (57% identical), Caenorhabditis elegans arrd-16 (26% identical), Caenorhabditis elegans arrd-7 (21% identical), Caenorhabditis elegans arrd-19 (21% identical), and 8 more. Paralogues in human: ARRDC3 (50% identical), ARRDC2 (44% identical), TXNIP (41% identical), ARRDC1 (24% identical), ARRDC5 (18% identical).
Diseases named in the same sentence as ARRDC4 in open-access papers:
ARRDC4 is named in the same sentence as 24 diseases in open-access papers, as found by Europe PMC text mining. Sharing a sentence is not in itself a finding about the gene and the disease. The quoted sentences say what the papers report.
breast carcinoma (3 papers, 2010 to 2013). "The expression of ARRDC4 was also positively associated with the predicted lactic acidosis pathway activity in these two breast cancer datasets." (PMID 20844768, 2010). "When breast cancers were stratified by the level of ARRDC4, tumors with higher levels of ARRDC4 had better prognosis and clinical outcome in the both breast cancer data (Miller and Pawitan) in which ARRDC4 was measured." (PMID 20844768, 2010). "A few genes previously reported to be induced by acidosis in breast cancer cells, including TXNIP, ARRDC4 and EGR2, were also noted to be induced in both HUVEC/Vector and HUVEC/GPR4 cells." (PMID 23613998, 2013).
lactic acidosis (3 papers, 2010 to 2021). Metabolic acidosis characterized by the accumulation of lactate in the body. "Expression levels of TXNIP and ARRDC4 in human cancers are also highly correlated with predicted lactic acidosis pathway activities and associated with favorable clinical outcomes." (PMID 20844768, 2010). "Importantly, the expression of TXNIP and ARRDC4 are tightly associated with predicted lactic acidosis pathway activities and correlated with favorable clinical outcomes in human cancers." (PMID 34916487, 2021). "As a key paralogue of thioredoxin interacting protein (TXNIP), ARRDC4 involves in suppressing cancer glycolytic phenotypes under lactic acidosis." (PMID 34916487, 2021). "For example, genes such as TXNIP and ARRDC4, which are both indicative of lactic acidosis, correlate with better clinical outcomes, and contribute to predicting tumors with intact NF1 signaling." (PMID 28166733, 2017). "Among these selected genes, TXNIP and its paralogue ARRDC4 are both induced under lactic acidosis and repressed with glucose deprivation." (PMID 20844768, 2010). "We detected increased specific binding of MondoA to the promoter regions of TXNIP and ARRDC4 with more acidic lactic acidosis environments." (PMID 20844768, 2010). "Therefore, the expression of both TXNIP and ARRDC4 are potentially important mediators of the lactic acidosis response and suggest the important prognostic significance of molecular pathways driven by Mondo-Mlx in human cancers." (PMID 20844768, 2010). "Our findings identify lactic acidosis as a novel stimulus for the activation of MondoA and induction of TXNIP/ARRDC4." (PMID 20844768, 2010). "MondoA is likely to be more relevant in the observed lactic acidosis response of MCF-7 given its higher expression levels in MCF-7 and the simultaneous upregulation of both TXNIP and ARRDC4 under lactic acidosis." (PMID 20844768, 2010). "When we examined expression of MCF-7 and HMEC under lactic acidosis at different time points, we also noted significant induction of TXNIP and its parralogue alpha-arrestin domain containing 4 (ARRDC4)." (PMID 20844768, 2010). "We first tested the influence of lactic acidosis on the reporter constructs driven by the promoters of TXNIP and ARRDC4 and found that lactic acidosis could induce the reporter activities of both constructs by more than 6 folds." (PMID 20844768, 2010).
colorectal cancer (2 papers, 2021 to 2022). A primary or metastatic malignant neoplasm that affects the colon or rectum. "It’s worth to investigate the targets of ZEB1 regulating by cooperation of METTL14, YHTDF2, ARRDC4, TCF4 and HuR leads to elevation of invasiveness and migration of colorectal cancer cells in the future study." (PMID 34916487, 2021).
Insulin resistance (2 papers, 2022 to 2023). Increased resistance towards insulin, that is, diminished effectiveness of insulin in reducing blood glucose levels. "Since we found glucagon resistance and insulin resistance phenotypes in the absence of ARRDC4, we measured circulating levels of ketone bodies in the ARRDC4KO mice." (PMID 37451484, 2023).
asthma (1 paper, 2024). "Single gene GSEA analysis revealed that HORMAD2, WNT10A, ATP6V1E2, CMBL, ARRDC4, and LPIN2 were primarily involved in Allograft rejection, Arginine biosynthesis, Asthma, and Fatty acid biosynthesis." (PMID 40635857, 2024).
colon cancer (1 paper, 2024). "A recent study demonstrated that brusatol could inhibit the malignant behaviors of colon cancer by upregulating ARRDC4 expression-a cancer glycolytic inhibitor- while modulating PI3K/YAP1/TAZ pathway." (PMID 38581008, 2024).
diabetes (1 paper, 2023). "cg10217853, located within ARRDC4, has been identified as a novel CpG site in this study, and arrestin domain–containing protein 4 is associated with diabetes by regulating insulin resistance and lipid metabolism in β cells in response to glucose." (PMID 38137029, 2023).
glioma (1 paper, 2013). A benign or malignant brain and spinal cord tumor that arises from glial cells (astrocytes, oligodendrocytes, ependymal cells). "And the target genes for SOX2 binding regions in glioma cells were identified, such as ARRDC4, PDE4D, BASP1 and so on." (PMID 24565222, 2013).
Hyperglycemia (1 paper, 2023). An increased concentration of glucose in the blood. "ARRDC4 deficiency seems to exacerbate both hyperglycemia and low glucose levels by failing to regulate gluconeogenesis." (PMID 37451484, 2023).
Hyperinsulinemia (1 paper, 2023). An increased concentration of insulin in the blood. "Mice that lacked ARRDC4 also had impaired suppression of hepatic glucose production in hyperinsulinemic–euglycemic clamps during both normoglycemia and hyperinsulinemia." (PMID 37451484, 2023).
influenza infection (1 paper, 2025). "The same study also reported another unique modulatory mechanism where arrestin domain-containing 4 (ARRDC4) senses influenza infection and regulates innate immunity through the muscle variant of the PFK1 metabolic axis, leading to antiviral activity." (PMID 41511331, 2025).
liver cancer (1 paper, 2023). An epithelial or non-epithelial malignant neoplasm that arises from the liver. "We performed coimmunoprecipitation experiments in HEPG2 human liver cancer cell lines that were transfected with human glucagon receptor-GFP + human ARRDC4-FLAG or glucagon receptor + empty vector controls and treated with glucagon or PBS." (PMID 37451484, 2023).
ovarian carcinoma (1 paper, 2017). A malignant neoplasm originating from the surface ovarian epithelium. "In addition, KLF4 was identified as a putative upstream regulator of drug resistance in ovarian cancer and together with ST3GAL5, SYNE1, CXCL8, HERC5, FOSL1, ARRDC4 merits further studies." (PMID 28473707, 2017).
prostate carcinoma (1 paper, 2021). A carcinoma that arises from epithelial cells of the prostate gland. "siRNAs targeting UBXN1 and ARRDC4 were used to knockdown the expression of these genes in prostate cancer cells." (PMID 34680357, 2021). "In this study, we found that germline variants of ARRDC4 and UBXN1 could affect the prostate cancer Gleason score, which could be a potential marker to select aggressive PCa." (PMID 34680357, 2021). "Therefore, to further analyze the possible mechanism of UBXN1 and ARRDC4 in invasion, apoptosis and EMT of prostate cancer cells, Western blotting was used to characterize the protein levels of p-PI3K, PI3K, p-Akt, Akt, and NF-κB." (PMID 34680357, 2021). "Knockdown of ARRDC4 does not affect migration of DU145 and LNCaP prostate cancer cells." (PMID 34680357, 2021).
cancer (8 papers, 2010 to 2024). A tumor composed of atypical neoplastic, often pleomorphic cells that invade other tissues. "Further support for both TXNIP and ARRDC4’s role in regulating GDF15 after the induction of ROS comes from a pan cancer meta-analysis assessing the impact of metformin (which has been reported to inhibit ROS) on gene expression." (PMID 39103698, 2024). "ARRDC2, ARRDC4, and TXNIP share common association with certain neurodegenerative diseases, while ARRDC1 is implicated in cancer." (PMID 38270169, 2024). "The rs200944490 (ARRDC4) and rs117555780 (UBXN1) were identified as candidate markers predictive of PCa Gleason score which is strongly associated with cancer aggressiveness." (PMID 34680357, 2021). "In addition, the results from IHC staining indicated that ARRDC4 expression was notably increased in CRC compared with adjacent para-cancer tissue." (PMID 34916487, 2021). "For instance, YTHDF2 recognizes the methylation of suppressor of cytokine signaling 2 (SOCS2) and arrestin domain-containing protein 4 (ARRDC4) and induces their mRNA degradation thus enhances metastasis and dissemination of cancer cells." (PMID 35974338, 2022). "Since epithelial-to-mesenchymal transition (EMT) actively relates to the invasion and metastasis of cancer cells, the expression of EMT markers such as vimentin and E-cadherin in PCa cells following knockdown of UBXN1 and ARRDC4 was characterized." (PMID 34680357, 2021). "Among the 24 potential genes, HSP90AA1, ANXA1, ARRDC4 and PSAT1 were involved with cancer progression." (PMID 34916487, 2021).
ARRDC4 also shares sentences with these, for which no sentence is quoted: infection (3 papers); epididymitis (1); gastric cancer (1); Infertility (1); lymphoma (1); neurodegenerative disease (1); Obesity (1); sarcoma (1); type 2 diabetes (1).